FIP1L1 (factor interacting with PAPOLA and CPSF1)
Diseases named in the same sentence as FIP1L1 in open-access papers (continued):
Sharing a sentence is not in itself a finding about the gene and the disease.
T-lymphoblastic lymphoma (2 papers, 2012 to 2022). The most frequent type of lymphoblastic lymphoma. "In humans, concurrent myeloid neoplasms and T lymphoblastic lymphoma have been reported with FIP1L1-PDGFRA fusion genes but not with any PDGFRB rearranged genes." (PMID 22356850, 2012).
bladder cancer (1 paper, 2019). "After treatment of bladder cancer cells with the siRNAs, the expression of circ5912 decreased 4.3-fold in T24 cells and 3.6-fold in SW780 cells, while the level of FIP1L1 remained unchanged." (PMID 31808751, 2019).
cardiac hypertrophy (1 paper, 2025). "Additionally, cases of endocardial involvement and cardiac hypertrophy due to eosinophilic infiltration are predominantly seen in patients with the FIP1L1-PDGFRα mutation." (PMID 40144421, 2025).
chronic myelomonocytic leukemia (1 paper, 2014). A myelodysplastic/myeloproliferative neoplasm which is characterized by persistent monocytosis, absence of a Philadelphia chromosome and BCR/ABL fusion gene, fewer than 20 percent blasts in the bone marrow and blood, myelodysplasia, and absence of PDGFRA or PDGFRB rearrangement. "In contrast to rearrangements involving PDGFRB, the FIP1L1- PDGFRA rearrangement is exceedingly rare in the setting of chronic myelomonocytic leukemia." (PMID 24669761, 2014). "Only a single report has described the identification of FIP1L1-PDGFRA in chronic myelomonocytic leukemia (CMML)." (PMID 24669761, 2014).
chronic neutrophilic leukemia (1 paper, 2014). A rare chronic myeloproliferative neoplasm characterized by neutrophilic leukocytosis. "We recently described a case of chronic neutrophilic leukemia associated with FIP1L1- PDGFRA rearrangement." (PMID 24669761, 2014).
colorectal cancer (1 paper, 2025). A primary or metastatic malignant neoplasm that affects the colon or rectum. "Notably, SRSF3, CPSF3, FIP1L1, CTR9, NUDT21, and CSTF2, among others, were found to exhibit a more significant contribution to the differential 3′-UTR gene expression in colorectal cancer." (PMID 40702779, 2025).
Hodgkin’s disease (1 paper, 2019).
mastocytosis (1 paper, 2009). A clonal myeloproliferative neoplasm characterized by the proliferation and accumulation of neoplastic mast cells in one or multiple organs or organ systems. "Patients with CEL and HES responded to imatinib and remained in complete haematological, clinical and molecular (for carriers of FIP1L1-PDGFRA rearrangement) remission for a median of 28.2 months (range: 11–54), whilst the patient with systemic mastocytosis did not respond." (PMID 19187542, 2009).
metastatic tumor (1 paper, 2026). "These mutations were all absent in metastatic tumor samples, which presented with FIP1L1 and NRIP1 not observed in the primary tumor samples." (PMID 41614915, 2026).
myocarditis (1 paper, 2022). Myocarditis is a condition that is characterized by inflammation of the heart muscle (myocardium). "The patient presented left ventricular dysfunction due to myocarditis associated with FIP1L1–PDGFRA rearrangement." (PMID 36042524, 2022).
Obesity (1 paper, 2025). Accumulation of substantial excess body fat. "Additionally, the genetic variants within FIP1L1 were also linked to the obesity-related traits and the MR analysis revealed that its muscle gene expression is positively associated with improved health outcomes, underscoring the important roles of FIP1L1 in human health." (PMID 40766245, 2025).
parasitic infection (1 paper, 2024). "In this case, the absence of clonal markers, such as the FIP1L1-PDGFRA fusion gene, and the lack of identifiable secondary causes, including parasitic infection or drug reaction, supported the diagnosis of iHES." (PMID 39575363, 2024).
pericardial effusion (1 paper, 2009). Fluid collection within the pericardial sac, usually due to inflammation. "Although he was found to be negative for the FIP1L1-PDGFRα mutation, his cardiac complications included pericardial effusion and restrictive cardiomyopathy, without myocardial necrosis." (PMID 20975799, 2009).
tumor (13 papers, 2009 to 2026). "Endomyocardial fibrosis and thrombus formation as well as cardiac arrest are also seen in patients with eosinophil-rich neoplasms carrying the FIP1L1-PDGFRA fusion gene or other PDGFR variants." (PMID 34052871, 2021). "In patients with chronic, eosinophil-rich, neoplasms exhibiting FIP1L1-PDGFRA or other imatinib-sensitive PDGFR variants, imatinib is regarded standard first-line therapy." (PMID 34052871, 2021). "In addition, strong inhibition of proliferation was observed in EOL1 cells (IC50 of 0.2±0.1 nM), a hypereosinophilic tumour cell line expressing the FIP1L1-PDGFRα chimeric protein, which is associated with chronic eosinophilic leukaemia." (PMID 19789626, 2009). "While limited literature has shown the association between FIP1L1 and metastases, NRIP1 is involved in the epithelial-to-mesenchymal transition, or EMT, which can lead to tumor migration and invasion." (PMID 41614915, 2026). "The importance of detecting the FIP1L1-PDGFRA rearrangement in hematopoetic neoplasms cannot be understated as this fusion protein is exquisitely sensitive to imatinib." (PMID 26457233, 2015). "The identification of the FIP1L1- PDGFRA fusion gene is significant since imatinib has excellent efficacy at low doses (100-400 mg daily) in FIP1L1-PDGFRA-positive neoplasms." (PMID 24669761, 2014). "His tumor was analyzed using OncoPanel, and a FIP1L1-PDGFRA rearrangement was detected." (PMID 26457233, 2015). "Our clinical NGS assay detected an unanticipated FIP1L1-PDGFRA rearrangement in his tumor." (PMID 26457233, 2015). "Indeed the prognosis changes when the FIP1L1-PDGFRA+ neoplasm turns out to be an acute leukemia." (PMID 34052871, 2021). "Other low frequency actionable fusions namely, AGK-BRAF, FIP1L1-PDGFRA, FNDC3B-PIK3CA, RET-NCOA4, SND1-BRAF, TMEM178B-MET, TMEM178B-BRAF, KANK1-NTRK3, EIF3E-RSPO2 and PTPRK -RSPO3 have been previously reported as rare fusions in tumours of other type." (PMID 35984852, 2022). "We report a FIP1L1–RARA fusion in a child with APL who presented with an extramedullary tumor in the skull without the classic karyotype using NGS, whom we treated with good results." (PMID 34249738, 2021). "Taken together, S116836 may have clinical efficacy against human neoplasms driven by FIP1L1-PDGFRα and other forms of activated PDGFRα regardless of the mutation status." (PMID 25431951, 2014). "Results showed that the exon skipping events of FIP1L1, NKTR, and ADD3, but not ATP5F1C, occurred in most tumor tissues highly expressing CDYL2a compared to matched normal breast tissues." (PMID 32373210, 2020).
cancer (4 papers, 2013 to 2022). A tumor composed of atypical neoplastic, often pleomorphic cells that invade other tissues. "Recently, some studies have focused on the role of some mRNA 3′ end-processing factors in cancer, including FIP1L1, CSTF50, CSTF2 and Neo-PAP." (PMID 24358221, 2013).
hematologic malignancies (2 papers, 2020 to 2022). "Obvious differences between APL with FIP1L1::RARA and other hematologic malignancies were identified." (PMID 36776354, 2022).
heart disease (1 paper, 2021). "Further potentially disease-relevant protein candidates without a known functional relation to hypertrophy, fibrosis or decompensated heart disease were SLTM, HNRNPLL, FIP1L1, RNMT, KRT18 and PUF60 and the downregulated NUDT4, GCAT, KIDINS220 and ARVCF." (PMID 34937869, 2021).
infection (1 paper, 2015). The state of being infected such as from the introduction of a foreign agent such as serum, vaccine, antigenic substance or organism. "Several infection-induced SUMO targets also are involved in mRNA maturation events, such as 3′ end pre-mRNA processing (CPSF1, CPSF2, FIP1L1, RBBP6, and WDR33), splicing (CLASRP, SFPQ, and ZRANB2), and nuclear RNA quality control (ZC3H18, ZCCHC7, and PAPD5)." (PMID 26549460, 2015).
musculoskeletal diseases (1 paper, 2018). "Therefore, we carried out a PCR analysis and observed that FIP1L1 and OLIG3 are indeed expressed in these tissues supporting their potential role in musculoskeletal diseases." (PMID 30157244, 2018).
FIP1L1 also shares sentences with these, for which no sentence is quoted: eosinophilic granulomatosis with polyangiitis (3 papers); Hematopoietic neoplasm (2); acute megakaryoblastic leukemia (1); anaplastic large cell lymphoma (1); asthma (1); atopic dermatitis (1); B-cell lymphomas (1); chronic myeloid leukemia (1); COVID-19 (1); gastrointestinal stromal tumor (1); heart failure (1); intimal sarcoma (1); lymphoblastic lymphoma (1); lymphoma (1); Mitral regurgitation (1); myelodysplastic syndrome (1); overlap syndrome (1); primary myelofibrosis (1); prostate carcinoma (1); restrictive cardiomyopathy (1); retinoblastoma (1); sarcoma (1); Thrombocytopenia (1); thrombosis (1); thrombotic thrombocytopenic purpura (1); transient ischemic attack (1); Vestibular Neuritis (1).